DNAH10 (dynein axonemal heavy chain 10)
Description:
Force generating protein of respiratory cilia. Produces force towards the minus ends of microtubules. Dynein has ATPase activity; the force-producing power stroke is thought to occur on release of ADP. Involved in sperm motility; implicated in sperm flagellar assembly. Probable inner arm dynein heavy chain.
Synonyms: FLJ43808; SPGF56
Tractability: Small molecule: a structure with a bound ligand is known. PROTAC: ubiquitination databases record sites on it.
Gene: Protein-coding gene on chromosome 12 (123,762,188 to 123,935,720, forward strand). Ensembl gene ENSG00000197653.
Subcellular location: Cytoplasm, cytoskeleton, cilium axoneme
Subcellular location (Human Protein Atlas): Principal piece
Gene Ontology:
Molecular function: dynein intermediate chain binding; dynein light intermediate chain binding; minus-end-directed microtubule motor activity; ATP binding
Biological process: cilium movement involved in cell motility; microtubule-based movement
Cellular component: sperm principal piece; 9+2 motile cilium; dynein complex; axoneme; sperm flagellum
Genetic constraint (gnomAD): Loss-of-function variants: 345 observed, 494 expected, observed/expected ratio (o/e) 0.7, 90% interval 0.64 to 0.76. The upper end of that interval is the gene's LOEUF score, 0.76, which puts it in group 3 of 6, group 1 being the genes least tolerant of losing a copy. Missense variants: 5,128 observed, 5,865.4 expected, observed/expected ratio (o/e) 0.87, 90% interval 0.85 to 0.89. Synonymous variants: 2,040 observed, 2,224 expected, observed/expected ratio (o/e) 0.92, 90% interval 0.88 to 0.95.
Gene-disease validity (ClinGen):
ClinGen rates the evidence that DNAH10 causes each of these diseases.
spermatogenic failure 56 (autosomal recessive): Moderate.
primary ciliary dyskinesia (autosomal recessive): Limited. A rare, genetically heterogeneous, primarily respiratory disorder characterized by chronic upper and lower respiratory tract disease.
Homologues: Orthologues: chimpanzee DNAH10 (98% identical), macaque DNAH10 (95% identical), mouse Dnah10 (88% identical), rat Dnah10 (87% identical), pig DNAH10 (87% identical), guinea pig DNAH10 (85% identical), tropical clawed frog dnah10 (77% identical), zebrafish dnah10 (70% identical), Drosophila melanogaster Dhc98D (49% identical), dog DNAH10 (19% identical). Paralogues in human: DNAH2 (32% identical), DNAH9 (31% identical), DNAH5 (30% identical), DNAH17 (30% identical), DNAH8 (30% identical), DNAH11 (29% identical), DNAH6 (29% identical), DNAH1 (28% identical), DNAH7 (28% identical), DNAH3 (28% identical), DNAH12 (27% identical), DNAH14 (25% identical), and 3 more.
Diseases named in the same sentence as DNAH10 in open-access papers:
DNAH10 is named in the same sentence as 26 diseases in open-access papers, as found by Europe PMC text mining. Sharing a sentence is not in itself a finding about the gene and the disease. The quoted sentences say what the papers report.
male infertility (3 papers, 2020 to 2024). The inability of the male to effect fertilization of an ovum after a specified period of unprotected intercourse. "For example, mutations in IDA and ODA genes, such as DNAH1, DNAH2, DNAH8, and DNAH10, cause male infertility due to asthenozoospermia with multiple morphological abnormalities of the sperm flagella." (PMID 36726469, 2022). "Additionally, other DNAHs, such as DNAH1, DNAH2, DNAH8, DNAH10, DNAH12, and DNAH17, are suggested to be pathogenic genes of isolated male infertility." (PMID 39503742, 2024).
clear cell renal cell carcinomas (2 papers, 2019 to 2022). "Increased incidence of non-synonymous single-nucleotide mutations and insertions/deletions was found in DNAH2, DNAH5, and DNAH10 genes of CpG-island methylator phenotype positive clear cell renal cell carcinomas." (PMID 35501919, 2022). "DNAH2, DNAH5 and DNAH10 have been reported to have an elevated incidence of nonsynonymous single-nucleotide mutations and indels in CIMP-positive clear cell renal cell carcinomas." (PMID 30944005, 2019).
amyotrophic lateral sclerosis (1 paper, 2025). Amyotrophic lateral sclerosis (ALS) is a neurodegenerative disease characterized by progressive muscular paralysis reflecting degeneration of motor neurons in the primary motor cortex, corticospinal tracts, brainstem and spinal cord. "DNAH10 (Duroc) and DNAI2 (Landrace) are involved in the biological process of amyotrophic lateral sclerosis." (PMID 39943208, 2025).
Anxiety (1 paper, 2023). Intense feelings of nervousness, tension, or panic often arise in response to interpersonal stresses. "Multiple high-confidence ASD risk genes associated with anxiety were dysregulated in our RNA-seq data including TMLHE and GRID2, DNAH10, GRIA1, SLC6A4, and IGF1." (PMID 37486945, 2023).
atrial fibrillation (1 paper, 2024). A disorder characterized by an electrocardiographic finding of a supraventricular arrhythmia characterized by the replacement of consistent P waves by rapid oscillations or fibrillatory waves that vary in size, shape and timing and are accompanied by an irregular ventricular response. "In the DisGeNET database, DNAH10 is associated with atrial fibrillation with a score of 0.4." (PMID 38952424, 2024).
chronic bronchitis (1 paper, 2025). A type of chronic obstructive pulmonary disease characterized by chronic inflammation in the bronchial tree that results in edema, mucus production, obstruction, and reduced airflow to and from the lung alveoli. "We further generated Dnah10 knockout (KO) mice and the Dnah10 KO male mice resembled the phenotype observed in the two PCD patients in these families, showing chronic bronchitis, the same striking defects in cilia structure, and motile frequency." (PMID 40898283, 2025).
cutaneous melanoma (1 paper, 2022). A primary melanoma arising from atypical melanocytes in the skin. "Among them, PKHD1L1, LRP1B, ADGRV1 and DNAH10 were hypomethylated in UV-mutant compared with non UV-mutant cutaneous melanoma patients in BCH." (PMID 35840550, 2022).
Insulin resistance (1 paper, 2019). Increased resistance towards insulin, that is, diminished effectiveness of insulin in reducing blood glucose levels. "DNAH10 was an inner arm dynein heavy chain, and reported to involve with pathogenesis of human insulin resistance." (PMID 31102348, 2019).
lipodystrophy (1 paper, 2023). A congenital or acquired disorder characterized by abnormal loss or redistribution of the adipose tissue in the body. "The weighted loci in this cluster (N = 37 loci) are lipodystrophy and adiposity-related variants (PPARG, IRS1, LYPLAL1, and DNAH10)." (PMID 37790568, 2023).
lung carcinoma (1 paper, 2020). "If new lung cancer patients are diagnosed with SCLC, patients could be sequenced using WES or target sequencing (including DNAH10)." (PMID 31959735, 2020).
ovarian carcinoma (1 paper, 2023). A malignant neoplasm originating from the surface ovarian epithelium.
pancreatic carcinoma (1 paper, 2019). "In conclusion, on the basis of TCGA sequence data, we proposed a four genes model (DNAH10, HSBP1L1, KIAA0513, and MRPL3), which facilitated the discernment of high‐risk patients for worse OS in pancreatic carcinoma." (PMID 31102348, 2019).
primary ciliary dyskinesia (1 paper, 2025). "In the present study, we demonstrated the presence of loss-of-function mutations in the DNAH10 gene among two families affected by primary ciliary dyskinesia." (PMID 40898283, 2025). "To date, only one study reported one individual with primary ciliary dyskinesia carried DNAH10 mutation." (PMID 40898283, 2025).
psoriasis (1 paper, 2019). An autoimmune condition characterized by red, well-delineated plaques with silvery scales that are usually on the extensor surfaces and scalp. "However, DNAH10 staining in the epidermis of the lesional skin showed less pronounced patterning, suggesting that psoriasis-associated alterations may disrupt DNAH10 expression patterning." (PMID 31836722, 2019). "Future therapeutic approaches may involve intervention in the early phase of wound healing, or in pathological skin conditions like psoriasis, by chemical or physical means to interfere with either target proteins like DNAH10, axonemal signaling, or with signaling cascades." (PMID 31836722, 2019). "Expression of DNAH10 in the epidermis was validated using immunohistochemistry in unrelated samples from control patients, as well as non-lesional samples from psoriasis patients’ epidermis." (PMID 31836722, 2019).
pulmonary fibrosis (1 paper, 2025). Chronic progressive interstitial lung disorder characterized by the replacement of the lung tissue by connective tissue, leading to progressive dyspnea, respiratory failure, or right heart failure. "Collectively, our findings demonstrated that DNAH10 deletion led to pulmonary fibrosis in Dnah10 KO mice." (PMID 40898283, 2025). "Defects in DNAH10 led to an aberrant immune response, pulmonary fibrosis, and disrupted mitochondrial metabolic processes." (PMID 40898283, 2025). "Subsequently, we investigated the pulmonary fibrosis phenotype in Dnah10 KO mice." (PMID 40898283, 2025). "Functionally, we observed that the absence of DNAH10 led to pathway enrichment in pulmonary fibrosis and abnormal mitochondrial metabolic processes, as revealed by proteomic analysis." (PMID 40898283, 2025).
Respiratory tract infection (1 paper, 2025). An infection of the upper or lower respiratory tract. "The fluorescence intensity of these inflammatory cell markers was significantly intensified in the lungs of Dnah10 KO mice, showing severe respiratory tract infections in these animals." (PMID 40898283, 2025).
DNAH10 also shares sentences with these, for which no sentence is quoted: tumor (5 papers); asthenozoospermia (2); small cell lung carcinoma (2); Autoimmunity (1); inflammatory skin disorder (1); lung adenocarcinoma (1); Lung Squamous Cell Carcinoma (1); multiple sclerosis (1); Obesity (1); scoliosis (1).